DTNBP1 (dystrobrevin binding protein 1)
Diseases named in the same sentence as DTNBP1 in open-access papers (continued):
Sharing a sentence is not in itself a finding about the gene and the disease.
bipolar I disorder (1 paper, 2008). A bipolar disorder that is characterized by at least one manic or mixed episode. "Considering the short duration of treatment with antimanic agents in this study (36.5±19.9), the association between the DTNBP1 gene and the effects of antimanic drugs on the long-term treatment of bipolar I disorder should be confirmed." (PMID 20046352, 2008). "We previously reported an association between dysbindin gene (DTNBP1) variants and bipolar I disorder (BID)." (PMID 20046352, 2008).
cutis laxa (1 paper, 2020). Cutis laxa (CL) is an inherited or acquired connective tissue disorder characterized by wrinkled, redundant and sagging inelastic skin associated with skeletal and developmental anomalies and, in some cases, with severe systemic involvement. "Cutis laxa (EFEMP2) and Hermansky-Pudlak syndrome (DTNBP1)-related genes were enriched in mast cells." (PMID 32727470, 2020).
developmental delay (1 paper, 2012). "The deletion found in the SCAP patient harbors ATXN1, DTNBP1, JARID2, and NHLRC1 that we propose may be responsible for ASDs and developmental delay." (PMID 22480366, 2012).
epilepsy (1 paper, 2021). A brain disorder characterized by episodes of abnormally increased neuronal discharge resulting in transient episodes of sensory or motor neurological dysfunction, or psychic dysfunction. "Homozygous mutation of rs2619538 T > A likely promotes DTNBP1 expression and facilitates subsequent processes in epilepsy pathologies." (PMID 33679873, 2021). "Together with the trend of increasing DTNBP1 expression in epilepsy patients and animal models in this study, these are the first findings to demonstrate the genetic association of DTNBP1 with TLE." (PMID 33679873, 2021). "Together with the trend of increased DTNBP1 expression in epilepsy patients and animal models in the present study, we hypothesized that the homozygous mutation of rs2619538 T > A functions by promoting DTNBP1 expression and subsequent processes in epilepsy pathologies." (PMID 33679873, 2021). "Compared with control rats, the epilepsy model showed an approximately 87% increase (p = 0.000) in the expression of DTNBP1 mRNA, similar to the increased rate of DTNBP1 protein (approximately 35%, p = 0.044)." (PMID 33679873, 2021). "In addition, IHC confirmed the abnormal expression of DTNBP1 in the epilepsy model, indicating that hyperfunction of DTNBP1 is involved in epileptic seizures." (PMID 33679873, 2021). "To determine whether DTNBP1 expression is abnormal in epileptic activity, we established a rat epilepsy model according to a PTZ-induced protocol." (PMID 33679873, 2021). "To further identify whether DTNBP1 is abnormally expressed in human epilepsy patients, we used online GSE datasets of pathological brain samples from TLE patients and normal controls that were acquired by the same technique, Illumina HumanHT-12 V3.0 expression BeadChip arrays." (PMID 33679873, 2021).
epileptic seizures (1 paper, 2021). "In contrast, the expression of DTNBP1 was demonstrated to be increased in TLE patients and an animal model in this study; thus, behavioral observations and electrophysiological results of epileptic seizures in Dys1A-Tg mice and the related mechanisms should be further evaluated in the future." (PMID 33679873, 2021).
Obesity (1 paper, 2013). Accumulation of substantial excess body fat. "Here we report a 6p deletion of about 1 Mb encompassing five genes (ATXN1, DTNBP1, JARID2, MYLIP and GMPR), identified in a patient with severe ID, hypotonia, brain anomalies, EEG abnormalities, macrosomia, obesity, and ASDs with associated hyperactivity and behavioral abnormalities." (PMID 23324214, 2013).
prostate tumor (1 paper, 2023). "We visualized multiple genomic alteration events of the DBNDD1, DBNDD2, and DTNBP1 genes across a set of prostate tumor samples using OncoPrint using a query for alterations." (PMID 37569304, 2023).
substance-induced psychosis (1 paper, 2014). "DTNBP1 variants (including e.g., protective and risk haplotypes) are reported to affect susceptibility to substance-induced psychosis, and dysbindin-1 is involved in regulation of synaptic plasticity, neurotransmitter release, and membrane surface expression of NMDA and D2 receptors." (PMID 25298178, 2014).
testicular cancer (1 paper, 2023). A primary or metastatic malignant neoplasm that affects the testis. "However, expression of the DTNBP1 gene did not significantly differ between normal and tumor tissues in PCa, testicular cancer, and other cancers." (PMID 37569304, 2023).
psychiatric disorder (9 papers, 2010 to 2025). A disorder characterized by behavioral and/or psychological abnormalities, often accompanied by physical symptoms. "DTNBP1 encodes the dystrobrevin binding protein 1 which has been genetically linked to multiple psychiatric disorders, as well as cognitive and memory functions in healthy human subjects." (PMID 30108311, 2020).
neurodevelopmental disorder (4 papers, 2016 to 2022). A behavioral and cognitive disorder with onset during the developmental period that involves impaired or aberrant development of intellectual, motor, or social functions. "Hypermethylation of Agap1 is associated with neurodevelopmental disorders through interference with the cellular structure and internal functioning of neurons and through interactions with other genes, particularly the Dtnbp1 gene." (PMID 35893036, 2022). "Overall, our findings highlight the potential for genetic variants in DTNBP1 and other developmentally regulated genes to influence maturational programs, such as the GluN2B-GluN2A switch, which are relevant to neurodevelopmental disorders." (PMID 27134685, 2016). "The relevance of regionally specific loss of DTNBP1 expression to the pathophysiology of this neurodevelopmental disorder is highlighted by postmortem studies revealing a decrease in DTNBP1 expression in neurons of the dorsolateral prefrontal cortex and hippocampus." (PMID 27725886, 2016).
cancer (3 papers, 2022 to 2023). A tumor composed of atypical neoplastic, often pleomorphic cells that invade other tissues. "We performed a pan-cancer analysis with representative genes encoding dysbindin-1, dysbindin-2, and dysbindin-3, including the DTNBP1, DBNDD2, and DBNDD1 genes, respectively." (PMID 37569304, 2023). "Accumulating evidence has revealed that DTNBP1 plays functional roles in cancer prognosis." (PMID 34997064, 2022). "DTNBP1 was upregulated in many types of cancers, especially in HCC." (PMID 34997064, 2022). "However, DTNBP1 may be used as a universal predictor for OS in different kinds of cancer, which is need to be further confirmed." (PMID 34997064, 2022). "Our analysis of bioinformatics revealed that DTNBP1 is upregulated in several other cancer types, indicating that the specificity of DTNBP1 as a diagnostic marker for HCC may be not enough." (PMID 34997064, 2022). "To further investigate the potential signaling pathways involved in DTNBP1-inhibitory effects in cancer cells, we performed GSEA to explore the biological function of DTNBP1 upregulation in HCC, and “cell cycle” pathway was significantly enriched." (PMID 34997064, 2022). "Furthermore, we investigated the DTNBP1 gene expression profile in 33 cancer types both in both normal and paired tumor samples." (PMID 34997064, 2022).
tumor (3 papers, 2022 to 2023). "Consistent with the findings obtained from TCGA analysis, DTNBP1 mRNA level in tumor tissues was also significantly higher than that in normal liver tissues." (PMID 34997064, 2022). "The DTNBP1 expression levels were higher in tumor tissues than those in adjacent normal tissues." (PMID 34997064, 2022). "The mRNA levels of DTNBP1 were higher in tumor tissues than those in the normal controls." (PMID 34997064, 2022).
genetic disorder (1 paper, 2024). "The ENSG00000287626 transcript is located on chromosome 6 and overlaps with DTNBP1, a gene associated with the genetic disorder Hermansky–Pudlak syndrome (HPS), which has been reported to affect some patients with IBD." (PMID 38510241, 2024).
DTNBP1 also shares sentences with these, for which no sentence is quoted: major depression (4 papers); albinism (3); neuroblastoma (3); oculocutaneous albinism (3); pulmonary fibrosis (3); Alzheimer disease (2); depression (2); mental disorder (2); ocular albinism (2); ovarian cancer (2); acute myeloid leukemia (1); alcoholism (1); anxiety disorder (1); breast carcinoma (1); Chediak-Higashi syndrome (1); Childhood onset (1); ciliopathy (1); colon cancer (1); congenital neutropenia (1); Griscelli syndrome (1); Hermansky-Pudlak syndrome 7 (1); Huntington disease (1); infection (1); liver cancer (1); lung squamous cell carcinoma (1); memory impairment (1); Menkes syndrome (1); oculocutaneous albinism type 1 (1); pancreatic cancer (1); rectal cancer (1).
A further 5 diseases each share a sentence with DTNBP1 in 1 paper.